MMP9 (matrix metallopeptidase 9)
Diseases named in the same sentence as MMP9 in open-access papers (continued):
Sharing a sentence is not in itself a finding about the gene and the disease.
tumor (continued). "Suppressing HOTAIR upregulates the HOXA5 level and downregulates MMP2 and MMP9, which are critical players in tumor invasion and metastasis." (PMID 28931862, 2017). "Several studies have shown a critical role of MMP9 in tumor angiogenesis and have linked ICAM1 to intra-tumor microvessel density." (PMID 28977919, 2017). "In invasive tumor cells, two MMPs, MMP-2 and MMP-9, are predominantly upregulated and take crucial roles in invasion and metastatic spread of tumor." (PMID 29234420, 2017). "After transfer, MMP3 activates MMP9 in 3LL tumor cells, which improves the invasive ability of 3LL tumor cells." (PMID 29137230, 2017). "As MMP2 and MMP9 facilitates the detachment of tumor cells from primary tumor site and VEGF promotes dissemination via ERK2 and Ras, TIMP1 is directly involved in inhibition of MMP's and halt metastatic process." (PMID 29219852, 2017). "MMP-2 and MMP-9 of the MMP family have been thought to play important roles in the processes of tumor invasion and metastasis." (PMID 29280977, 2017). "The medical investigations of MMP-9 advance the cancer therapy and the prevention of tumor metastasis." (PMID 28969037, 2017). "Using species-specific primers, we found a significant increase in MMP-9 gene expression in the tumor-reactive stroma during late-stage metastasis in the lung." (PMID 28819116, 2017). "A further objective of this study was to correlate expression of serum MMP-9 with the expression of the same protein in the tumor tissue (the putative source of the biomarker)." (PMID 27757720, 2017). "Using MMP-9-deficient mice, Itoh and coworkers confirmed that MMP-9 mediates the process of tumor metastasis." (PMID 29280977, 2017). "These neutrophils contribute to the elevated levels of pro-metastatic molecules like S100A8, S100A9, Bv8, and MMP9 in the lungs, supporting tumor cell homing to this organ." (PMID 29340117, 2017). "The localization of MMP9 on the cell surface is required to promote tumor invasion and angiogenesis." (PMID 28191466, 2017). "More specifically, it has been seen that the expression of MMP-9 induced VEGF production in the TANs of tumor cells." (PMID 28149530, 2017). "Western blot analysis further showed that, after MIR4697HG knockdown in SKOV3 cells, the protein level of MMP-9, a biomarker of tumor metastasis, significantly decreased." (PMID 28168162, 2017). "Considering matrix metalloproteinases (MMPs), HCCLM3 cells from metastatic regions showed higher expression of MMP9 than cells from the primary tumor site." (PMID 28205428, 2017). "RERG increased the expression of TIMP-2 and inhibited the expression of MMP-2 and MMP-9, providing support for a mechanistic explanation of the inhibition of tumor microvessel growth and size by RERG." (PMID 28659184, 2017). "Recent studies have revealed that myeloid cells contribute to tumor vascularization via the angiogenic activity of matrix metalloproteinase MMP9/gelatinase-B and by differentiating into endothelial cells." (PMID 28423685, 2017). "Tumor vascularization involves a release of matrix-deposited VEGFA by MMP9 produced by various cells in the TME." (PMID 28977919, 2017). "Together these findings show that fibroblasts enhance tumor vascularization and tumor-derived MMP9 plays a critical role in this response." (PMID 28423685, 2017). "VEGFA is anchored by Fibronectin in the extracellular matrix, and then soluble VEGFA is released from matrix by metalloprotease MMP9 produced by tumor or infiltrating myeloid cells via TAK1 signaling." (PMID 28977919, 2017). "The expression of MMP-2 and MMP-9 were both higher in LL/2-R than LL/2-P cells, also higher in tumor tissues from LL/2-R than LL/2-P in mouse models." (PMID 28978115, 2017). "MMP9 has multiple functions, such as tumor growth and metastasis, and also plays a central role in inflammatory responses, such as tissue remodeling and wound healing." (PMID 29354126, 2017).
tumor (continued). "Trophoblast and tumor cells have similar invasion mechanisms and share similar biochemical mediators, such as c-Myc and MMP-9." (PMID 28606936, 2017). "MMP-9 is delivered into the tumor microenvironment by M2 macrophages, and subsequently sustains those distinct angiogenic vessels capable, supporting tumor cell intravasation and metastatic dissemination." (PMID 28423526, 2017). "MMP-2 and MMP-9 are thought to be important in tumor metastasis and tissue remodeling; therefore, the present study investigated the protein expression of MMP-2 and MMP-9 during the treatment of MCF-7 or MDA-MB-231 cells with propoxur." (PMID 29152067, 2017). "Since MMP-9 can promote the migration and metastasis of tumor cells through degradation of extracellular matrix (ECM) components, we next examined the effect of TBC1D3 on the expression and activation of this endopeptidase in MCF-7 cells." (PMID 28422741, 2017). "Together these results suggest that tumor-fibroblast co-cultures stimulate expression of cytokines which act upon tumor cells to co-operatively up-regulate MMP9 levels." (PMID 28423685, 2017). "MMP-9 is a protease widely studied because it is important to promote the whole process of cell colonization, hence proliferation, tumor invasion and metastasis." (PMID 28053600, 2017). "Our previous findings showed that BDM is a potent matrix metalloproteinase (MMP) inhibitor, especially the gelatinases (MMP‐2 and MMP‐9), that play important roles in tumor invasion, metastasis, and angiogenesis." (PMID 28211615, 2017). "In our study, piceatannol exerted a potent inhibitory effect on OSCC development in tumor xenograft mice in vivo and attenuated VEGF and MMP9 expression in tumor tissues." (PMID 29137391, 2017). "The NET component—matrix-metalloproteinase 9 (MMP-9)—participates in the degradation of the extracellular matrix, and it is involved in tissue remodeling, angiogenesis, and tumor progression." (PMID 27885378, 2017). "In mice, it has been reported that genetic ablation of MMP9 in APCMin+/− mice resulted in 40% fewer tumors than littermate controls, although tumor size distribution remained unaffected." (PMID 27861153, 2017). "Based on the immunohistochemical staining results, compared with the untreated doxycycline groups, E-cadherin and α-SMA exhibited high expression levels, whereas vimentin, MMP2 and MMP9 exhibited low expression in tumor tissue." (PMID 28187433, 2017). "Together these results revealed that TGF-β-type cytokines cooperate with TNF and IL-1β cytokines in the stimulation of MMP9 expression in tumor cells." (PMID 28423685, 2017). "After transfer, MMP3 exhibited a robust ability to activate MMP9 and promote tumor metastasis in vivo." (PMID 29137230, 2017). "This study reveals that tumor-associated fibroblasts enhance tumor growth, promoting the formation of tumor blood vessels via a mechanism requiring MMP9." (PMID 28423685, 2017). "Accordingly, secretion of MMP9 was significantly increased in tumor-fibroblast co-cultures and this effect was dependent on TGF-β signaling." (PMID 28423685, 2017). "MMP9 staining was mainly observed in tumor stromal cells (located in cell membranes and cytoplasm), including macrophages, ESCC tumor cells and endothelial cells (ECs)." (PMID 28423526, 2017). "MMP9 production and secretion by tumor cells are vital factors involved in the promotion of metastasis." (PMID 28109307, 2017). "To verify the regulation of TIMP2 by EZH2, we performed loss- and gain-of-function experiments of EZH2 and examined TIMP2 expression, MMP2 and MMP9 expression and proteolytic activity, and tumor cell migration and invasion." (PMID 28620234, 2017). "On anti-tumor activity, curcumin regulates metastasis-relating protein MMP-9 for reducing tumor metastasis." (PMID 28671583, 2017). "We first examined the effect of isothiocyanates on MMP-9 activity, which plays a critical role in tumor metastasis, and cancer cell migration." (PMID 28969043, 2017).
tumor (continued). "MMP-9 is produced principally by osteoclasts and immune cells, which have been reported to be important for tumor growth." (PMID 29152067, 2017). "Tumor-fibroblast co-cultures secreted an active 85kDa form of MMP9 that accumulated over the time of incubation." (PMID 28423685, 2017). "Matrix metalloproteinases (MMPs) including MMP-2, MMP-7, and MMP-9 are known to promote tumor progression and cancer stemness." (PMID 29340100, 2017). "As the biological functions of MMP9 in maintenance of tumor stem cells and metastatic niches are well established, there has been a lot of research interest in the MMP9 gene and its SNPs." (PMID 29138529, 2017). "We also found increased MVD was correlated with higher expression of MMP9 in Kazakh ESCC tumor tissues." (PMID 28423526, 2017). "MMP-9 expression was observed in tumor cells and tumor-infiltrating neutrophils in Min/OPN(+/+) mice." (PMID 28505114, 2017). "Studies have shown that MMPs, particularly MMP-2 and MMP-9, play a role in tumor angiogenesis, invasion, and metastases." (PMID 29138529, 2017). "MMP-9 expression was observed strongly in stromal infiltrating neutrophils, and weakly in cancer cells in tumor tissue in Min/OPN(+/+) mice." (PMID 28505114, 2017). "Depletion of JUN and JUNB or disruption of TAK1-RELA signaling blocked the cytokine-mediated induction of MMP9 in tumor cells." (PMID 28423685, 2017). "Among these are two highly associated with tumor dissemination and invasiveness: MMP-2 (aka gelatinase A) and MMP-9 (aka gelatinase B), which degrade type IV collagen and gelatin substrates." (PMID 28633655, 2017). "Matrix metalloproteinases (MMPs), MMP2 and MMP9 in particular, have been regarded as major molecules that assist tumor cells by cleaving several ECM components and it paves the way for detachment and dissemination during metastasis." (PMID 29219852, 2017). "Based on our observation that MMP-9 was significantly elevated at late stage metastasis in tumor cells in vivo, we focused in particular on tumor- derived TGF- β1 in regulating MMP-9 expression." (PMID 28819116, 2017). "Next, we examined the secretion of MMP9 in fibroblast and tumor cells alone, as well as in co-cultures using in-gel gelatin zymography assays." (PMID 28423685, 2017). "MMP9 also plays roles in tumor development, as these proteins facilitate extracellular matrix remodeling and participate in angiogenesis." (PMID 28191466, 2017). "From results of the present study, up-regulation of MMP-9 appears to be directly mediated by TGF-β1 signaling from tumor cells since abrogation of TGF-β1 within tumor cells led to a decrease in MMP-9 levels." (PMID 28819116, 2017). "MMP-1, MMP-2 and MMP-9 were all increased in tumor samples compared with matched, corresponding normal tissues." (PMID 28915603, 2017). "MMP-9 is expressed in all hematopoietic cells and fibroblasts existing in the tumor microenvironment." (PMID 28677624, 2017). "To address the mechanism by which p38MAPK enhances tumor angiogenesis we examined the expression of MMP9 and ICAM1." (PMID 28977919, 2017). "In 87% of cases, the proteins belonged to pathways related to local tumor progression, metastasis and/or angiogenesis (i.e. cathepsin D, MMP-9, eNOS, Leptin, ANGPTL4, autotaxin)." (PMID 29245929, 2017). "MMP9 stimulates tumor vasculature by releasing and/or activating matrix-deposited pro-angiogenic growth factors, such as VEGF, thereby recruiting vasculature-forming endothelial cells and pericytes." (PMID 28423685, 2017). "Herein, we demonstrate that coactivation of EGF and EGFR drives tumor metastasis in a matrix metalloproteinase-9 (MMP-9)–dependent manner." (PMID 29029486, 2017).
tumor (continued). "Previous studies have reported that MMP-9, an indicator of tumor metastasis, was regulated by NF-κB." (PMID 28288190, 2017). "Our study shows that in CAC, MMP9 protects from genotoxicity as indicated by decreased levels of γH2AX and acts a tumor suppressor." (PMID 27861153, 2017). "COX-2 promotes the secretion and release of MMP-2 and MMP-9 to involve in tumor progression and metastasis." (PMID 28938623, 2017). "Evidence suggests a directly proportional relationship with elevated overexpression of MMP9 in invasive tumors and their clinical impact on tumor relapse." (PMID 27974694, 2017). "The antibody, GS-5745, is a humanized monoclonal antibody against MMP-9, which upon binding MMP-9 results in inhibition of ECM degradation and possibly a reduction in tumor growth and risk of metastasis." (PMID 28633655, 2017). "MMP-9 and MMP-2 are key enzymes that degrade type IV collagen, the major constituent of the basement membrane, and are mainly associated with tumor invasion, degradation of bone tissue, and angiogenesis." (PMID 28969043, 2017). "Tumor angiogenesis is stimulated by the influx of neutrophils that release highly angiogenic pro-MMP9 free of TIMP1, the natural inhibitor of MMP9, or M2 macrophages expressing high levels of pro-MMP9 and low levels of TIMP1." (PMID 28423685, 2017). "MDSCs are noted to secrete MMP9 to facilitate tumor invasion and metastasis and S100A8/9 to promote survival of cancer cells." (PMID 29142311, 2017). "Accumulating evidences also showed that DDR1 functioned as an inducer of MMP2 and MMP9, which contributed to matrix components degradation during tumor invasion." (PMID 28743276, 2017). "Specific ablation of MMP9 positive TAMs with zoledronic acid resulted in reduced tumor angiogenesis, leading to a conclusion that TAMs deliver angiogenesis-inducing MMP9 are implicated in invasion-promoting processes such as flicking of the angiogenic switch." (PMID 28423526, 2017). "Mechanistically, our findings argue that expression of MMP9 in tumor cellsis regulated by crosstalk of TGF-β with TNF and/or IL-1β cytokines." (PMID 28423685, 2017). "Further studies are required to decipher the molecular mechanism by which Rab1B interacts with MMP9 to promote tumor progression and metastasis in CRC." (PMID 28316326, 2017). "These evidences indicated different roles and different demands of MMP-2 and MMP-9 expression among tumor growth stages." (PMID 28606135, 2017). "We also noted that the tested cytokines induced a 92kDa zymogen form of MMP9 while the tumor-fibroblast co-cultures produced an active 85kDa form of MMP9, suggesting an additional level of MMP9 regulation in the cell co-cultures." (PMID 28423685, 2017). "It is well documented that MDSCs infiltrate into the tumor site and promote tumor angiogenesis through increased production of MMP-9 and VEGF5,17." (PMID 29070836, 2017). "Western blot analysis revealed that MMP2 and MMP9, two metalloproteinases which play critical roles in tumor invasion and migration, were also reduced after CCDC109B knockdown." (PMID 28754121, 2017). "It has been shown that GMI suppressed the EGF-mediated migration and invasion via blockage of PI3K/Akt pathway and the TNF-α-induced tumor invasion and inflammation through inhibition of NF-κB/MMP-9 pathway in human alveolar epithelial A549 cells." (PMID 29050290, 2017). "In this study, we investigated the mechanistic role of MMP9 in preserving the epithelial mucosal integrity to suppress the progression of tumor microenvironment in CAC." (PMID 29212256, 2017). "By means of northern blot analysis, increased expression of MMP-9 was detected in HCC patients especially in tumor portion around the capsule." (PMID 28216578, 2017). "According to a recent report, MMP9 secretion by TAMs recruited into the tumour site, in response to osteopontin signalling in melanoma, induced angiogenesis and tumour growth." (PMID 29065107, 2017).
tumor (continued). "Some studies show that Isothiocyanatesinhibited MMP-9 activity by inactivating FAK/ERK/AKT pathways in tumor cells." (PMID 29267213, 2017). "MMP-9, a marker for tumor distant metastasis, was also decreased by MIR4697HG knockdown in SKOV3 cells, which further confirmed MIR4697HG-mediated migration and invasion inhibition." (PMID 28168162, 2017). "Both the MAPK and AKT pathways are broadly reported to directly or indirectly regulate MMP-2 and MMP-9, as well as tumour migration and invasion." (PMID 28729634, 2017). "In contrast, MMP2, MMP9, and Cyclin D1 levels were decreased in tumour tissues with downregulated CEP55 expression." (PMID 28724890, 2017). "Depletion of MMP9 significantly reduced tumor growth in both the tumor alone and tumor-fibroblast groups." (PMID 28423685, 2017). "MMP-9 plays a crucial role in tumor invasion and angiogenesis by mediating degradation of the extracellular matrix." (PMID 28933726, 2017). "Stem cell factor‐stimulated mast cells produce matrix metalloprotease‐9 (MMP‐9) that facilitates recruitment of mast cells and other cells to the tumour." (PMID 28032353, 2017). "NF-κB regulates expression of MMP-9 such that inhibition of NF-κB activation suppresses MMP-9 and tumor invasion." (PMID 28920157, 2017). "Our in vitro experiments in cultured CRC cells strongly suggest that ANXA13-mediated the expression of the active form of MMP-9, which is known for its role in tumor metastasis." (PMID 28423508, 2017). "We observed that sunitinib-resistant LL/2 cancer cells exhibited increased migration and invasion in vitro, and enhanced metastatic potential in vivo, companied by MMP2 and MMP9 overexpression, which play crucial roles in tumor invasion and metastasis." (PMID 28978115, 2017). "MDSC-derived S100A8/A9 and MMP9 can pre-dispose the lung microenvironment to promote tumor metastasis." (PMID 29142311, 2017). "The activation of MMP-9/Notch signalling was associated with increased CRC cells invasiveness, suggesting a tumor-prone role of Notch1 signalling in sporadic CRC." (PMID 28785079, 2017). "The results of daily measurement of tumor diameters indicated that MMP-9 overexpression increased tumor size." (PMID 29029486, 2017). "Both over-expression of MGAT5 and MMP9 strongly correlates with poorer tumor differentiation, higher TNM stage, and poorer survival." (PMID 29069753, 2017). "MDSCs from tumor-bearing mice express higher levels of MMP9, thereby increasing the bioavailability of VEGF5 and have been reported to mediate tumor refractoriness to anti-VEGF treatment." (PMID 29070836, 2017). "Through our “proof of principle” model we verified the direct participation of MMP9 as a tumor suppressive protein, by using stably transfected MMP9−/− MEFs with re-expression of MMP9." (PMID 27861153, 2017). "Since MMP2, MMP7 and MMP9 are important for the degradation of the tumor matrix, we investigated their protein levels by Western blot and the activity of MMPs by zymography." (PMID 28250971, 2017). "Macrophage-derived TGF-β1 can promote MMP-9 expression in glioma stem-like cells, thereby enhancing the invasiveness of tumor cells." (PMID 28955335, 2017). "Later, researchers found that TIMP-1 also functions independently of MMP-9 to promote tumour growth and inhibit apoptosis." (PMID 29228747, 2017). "Knockdown of TGF-β1 expression in the tumor cells negatively affected matrix metalloproteinase (MMP)-9 gene expression." (PMID 28819116, 2017). "Expression of tumor-induced factors responsible for MDSCs’ differentiation and proliferation, such as, TGFβ, MMP9, IL-6, VEGF, CXCR4, CCL2 was upregulated in MDSCs from CD8 depleted NLGP immunized mice, that was in downregulation after NLGP treatment." (PMID 28414726, 2017). "We previously have shown that β6-1089 cells promote tumour invasion through TGF-β-mediated upregulation of MMP-9." (PMID 28330493, 2017).